MTM1 (myotubularin 1)
Description:
Lipid phosphatase which dephosphorylates phosphatidylinositol 3-monophosphate (PI3P) and phosphatidylinositol 3,5-bisphosphate (PI(3,5)P2). Has also been shown to dephosphorylate phosphotyrosine- and phosphoserine-containing peptides. Negatively regulates EGFR degradation through regulation of EGFR trafficking from the late endosome to the lysosome. Plays a role in vacuolar formation and morphology. Regulates desmin intermediate filament assembly and architecture. Plays a role in mitochondrial morphology and positioning. Required for skeletal muscle maintenance but not for myogenesis. In skeletal muscles, stabilizes MTMR12 protein levels.
Synonyms: CNM; CNMX; MTMX; XLMTM
Tractability: Antibody: UniProt places it where antibodies can reach, with high confidence; its Gene Ontology location is reachable by antibodies, with high confidence; the Human Protein Atlas places it where antibodies can reach. PROTAC: ubiquitination databases record sites on it; its protein half-life has been measured.
Gene: Protein-coding gene on chromosome X (150,568,417 to 150,673,143, forward strand). Ensembl gene ENSG00000171100.
Subcellular location: Cytoplasm; Cell membrane; Cell projection, filopodium; Cell projection, ruffle; Late endosome; Cytoplasm, myofibril, sarcomere
Subcellular location (Human Protein Atlas): Plasma membrane
Pathways (Reactome):
Metabolism: Synthesis of PIPs at the early endosome membrane; Synthesis of PIPs at the late endosome membrane; Synthesis of PIPs at the plasma membrane
Gene Ontology:
Molecular function: intermediate filament binding; phosphatidylinositol binding; phosphatidylinositol-3,5-bisphosphate 3-phosphatase activity; phosphatidylinositol-3-phosphate phosphatase activity; phosphoprotein phosphatase activity; protein binding
Biological process: endosome to lysosome transport; intermediate filament organization; mitochondrion distribution; mitochondrion organization; phosphatidylinositol dephosphorylation; protein dephosphorylation; regulation of vacuole organization; muscle cell cellular homeostasis; negative regulation of autophagosome assembly; phosphatidylinositol biosynthetic process
Cellular component: cytoplasm; filopodium; late endosome; plasma membrane; ruffle; cytosol; membrane; I band; sarcomere
Gene-disease validity (ClinGen):
ClinGen rates the evidence that MTM1 causes each of these diseases.
X-linked myotubular myopathy (X-linked): Definitive. A rare X-linked congenital myopathy characterized by numerous centrally placed nuclei on muscle biopsy and that presents at birth with marked weakness, hypotonia and respiratory failure.
Homologues: Orthologues: chimpanzee MTM1 (100% identical), macaque MTM1 (99% identical), dog MTM1 (96% identical), pig MTM1 (96% identical), guinea pig MTM1 (95% identical), rabbit MTM1 (94% identical), mouse Mtm1 (92% identical), rat Mtm1 (81% identical), zebrafish mtm1 (73% identical), tropical clawed frog mtm1 (72% identical), Drosophila melanogaster mtm (54% identical), Caenorhabditis elegans mtm-1 (42% identical), and 10 more. Paralogues in human: MTMR2 (65% identical), MTMR1 (58% identical), MTMR3 (36% identical), MTMR8 (35% identical), MTMR4 (35% identical), MTMR7 (34% identical), MTMR6 (34% identical), SBF1 (30% identical), SBF2 (29% identical), MTMR9 (29% identical), MTMR10 (25% identical), MTMR11 (21% identical), and 1 more.
Diseases named in the same sentence as MTM1 in open-access papers:
MTM1 is named in the same sentence as 77 diseases in open-access papers, as found by Europe PMC text mining. Sharing a sentence is not in itself a finding about the gene and the disease. The quoted sentences say what the papers report.
myotubular myopathy (66 papers, 2008 to 2026). "To investigate the mechanisms implicated in the pathology of XLCNM (also called myotubular myopathy), we integrated experimental omics data (transcriptomics, proteomics, metabolomics) obtained from Mtm1−/y mice and their WT littermates with public databases." (PMID 41373724, 2025). "The loss of T‐tubule components like bin1 and mtm1 results in the human disease known as centronuclear myopathy, which manifests with symptoms of myalgia, motor symptoms, respiratory symptoms, and exercise intolerance." (PMID 39840753, 2025). "Another significant BIN1_SH3 binder detected by our assay is MTMR1, a close paralog of myotubularin (MTM1) whose mutation can cause the X-linked form of CNM also called myotubular myopathy." (PMID 38995680, 2024). "X-linked myotubular myopathy (XLMTM) is a rare monogenic disease due to mutations in the MTM1 gene that cause centronuclear myopathy." (PMID 38678519, 2024). "XLMTM is a specific subtype of myotubular myopathy, which is a rare genetic neuromuscular disorder characterized by severe muscle weakness and hypotonia (low muscle tone) caused by mutations in the MTM1 gene." (PMID 37892232, 2023). "X-linked myotubular myopathy (XLMTM) is a severe form of centronuclear myopathy, characterized by generalized weakness and respiratory insufficiency, associated with pathogenic variants in the MTM1 gene." (PMID 36142184, 2022). "Myotubular myopathy 1 (MTM1) is an X-linked recessive centronuclear myopathy due to loss of function mutations in the myotubularin 1 (MTM1) at Xq28." (PMID 34198563, 2021). "XLMTM is a very rare congenital centronuclear myopathy caused by mutations in the MTM1 gene, affecting 1/50,000 boys." (PMID 33260623, 2020). "To date, more than 200 loss-of-function mutations of the MTM1 gene have been found in myotubular myopathy patients." (PMID 33255644, 2020). "There are multiple genetic forms of CNM along with an X-linked form known as myotubular myopathy (XLMTM) caused by mutations in the myotubularin (MTM1) gene." (PMID 33255644, 2020). "Myotubular myopathy) is caused by LoF mutations in the MTM1 gene, while autosomal dominant CNM (AD-CNM) is mostly caused by GoF mutations in the DNM2 gene." (PMID 33324928, 2020). "In skeletal muscle mutations in MTM1 or altered interaction between MTM1 and a number of binding partners, including AmpII lead to inherited centronuclear myopathies, some of which are associated with cardiomyopathies." (PMID 31043634, 2019). "The mutation of MTM1 is known to show a phenotype of myotubular myopathy, with inheritance of X-linked recessive." (PMID 27353517, 2016). "Loss of MTM1 in humans results in a disease known as myotubular myopathy and is characterized by severe muscle atrophy at birth, and mice lacking MTM1 show T-tubule disorganization with disrupted calcium homeostasis and excitation-contraction coupling defects." (PMID 27294373, 2016). "All of the female patients with MTM1 mutations included in the paper showed histological features related to a centronuclear myopathy, confirming previous published data." (PMID 27017278, 2016). "Centronuclear and myotubular myopathies (CNMs) are rare, inherited muscle disorders characterized by muscle atrophy, weakness, and altered muscle fiber structure, primarily caused by mutations in MTM1, DNM2, or BIN1." (PMID 41373724, 2025). "As myotubular myopathy is linked to loss of the MTM1 protein and/or activity and an increase in the levels of PtdIns3P, previous studies tested whether modulation of different PI3K isoforms could normalize PI levels in MTM1 loss-of-function models." (PMID 36943412, 2023). "In addition, NMJs are disrupted in preclinical models of centronuclear myopathy due to mutations in MTM1 or DNM2." (PMID 32804943, 2020). "Consequently, a consortium is testing its ASO candidate IONIS-DNM2–2.5Rx (DYN101) that is administered i.v. in patients with centronuclear myopathies caused by mutations in either DNM2 or MTM1 (NCT04033159)." (PMID 33324928, 2020).
myotubular myopathy (continued). "Similarly, the identification of DNM2 and BIN1 as genetic modulators of MTM1, all of which cause a centronuclear myopathy, indicates intimate crosstalk among genes involved in the same (or similar) disorders." (PMID 31413155, 2019). "In skeletal muscle, PIPs and their enzymatic regulators serve critically important functions exemplified by mutations of the PIP phosphatase MTM1 in myotubular myopathy (MTM), a severe muscle disease characterized by impaired muscle structure and abnormal excitation–contraction coupling." (PMID 24004519, 2013). "The deletion of MTM1 gene may be associated with our patient’s hyptonia as MTM1 deletions and mutations have been shown to be related to myotubular myopathy." (PMID 23634718, 2013). "Additionally, in 2024, a 3-year-old boy had myotubular myopathy caused by an MTM1 gene mutation." (PMID 41189975, 2025). "Within the group of centronuclear myopathies, MTM1, DNM2 and BIN1 are interconnected due to the role they play in membrane trafficking." (PMID 38678519, 2024). "Its beneficial effect on muscle function was demonstrated in preclinical models of BIN1, DNM2 and MTM1 related centronuclear myopathies." (PMID 38678519, 2024). "Preclinical studies showed that the downregulation of DNM2, whose levels are increased also in BIN1 and MTM1-related centronuclear myopathies, resulted in clinical and histological improvements." (PMID 38678519, 2024). "At 5 weeks, the Mtm1-KO mice display reduced fiber size with abnormal accumulation of oxidative staining, reminiscent of the histopathological hallmarks observed in myotubular myopathy patients." (PMID 36943412, 2023). "β1 Integrin is abnormally accumulated inside myofibers in the Mtm1-KO mouse and patients, most probably leading to the small, rounder myofibers and intracellular disorganization typical of myotubular myopathy." (PMID 36943412, 2023). "In certain pathological conditions, such as myotubular myopathy (MTM1), elevated levels of PiPs can decrease the intracellular Ca2+ concentration leading to weak muscles." (PMID 37108098, 2023). "Mutations in MTM1 and MTMR14 lead to inherited forms of centronuclear myopathy, while mutations in MTMR5, MTMR13, and MTMR2 are associated with a specific subtype of Charcot Marie Tooth disease (i.e., CMT4B), a demyelinating sensory neuropathy." (PMID 37680133, 2023). "Mtm1−/y mice recapitulate myotubular myopathy; as observed in patients, mice display a severe myopathic phenotype and a reduced lifespan." (PMID 35642830, 2022). "The pathological changes in the muscle biopsies of the EHBP1L1 variant that the affected Labrador Retrievers were similar to those described for Labrador Retrievers with a centronuclear myopathy caused by mutations in PTPLA and MTM1." (PMID 36011338, 2022). "Myotubular myopathy [also called X-linked centronuclear myopathy (CNM), XLCNM, XLMTM; OMIM 310400] is due to mutations in the phosphoinositide phosphatase myotubularin (MTM1)." (PMID 35642830, 2022). "Reduction of DNM2 by systemic delivery of ASOs was shown to rescue myotubular myopathy in 3-week-old Mtm1−/y mice in a dose–response manner." (PMID 35642830, 2022). "Lastly, we compared specific DEGs found with those described in a recent transcriptomic study that examined three centronuclear myopathy models, including Mtm1 KO mice." (PMID 35694952, 2022). "It has been reported that severe neonatal bulbar and respiratory muscle involvement occurs particularly in severe NM (most likely ACTA1-, NEB- or KLHL40-related) and MTM1-related myotubular myopathy." (PMID 35081925, 2022). "Mice knockout for MTM1 present with progressive centronuclear myopathy characterized by SR and TT disorganization, centrally positioned nuclei, and disorganized mitochondria distribution." (PMID 35454077, 2022). "Another two clinical trials to treat myotubular myopathy by MTM1 gene therapy or tamoxifen repurposing are also ongoing." (PMID 34768808, 2021).
myotubular myopathy (continued). "Mtm1-KO causes an overexpression of DNM2 and systemic administration of an ASO downregulating Dnm2 mRNA prevented and reverted myotubular myopathy in Mtm1-KO mice." (PMID 33324928, 2020). "MTM1 knockout (KO) mice evolve centronuclear myopathy, starting at around one month after birth, showing dynamic muscle weakness that critically decreases lifespan to a maximum of 2–3 months." (PMID 33255644, 2020). "Among these, mutations in myotubularin (MTM1), amphiphysin 2 (BIN1), and dynamin 2 (DNM2) lead to different forms of centronuclear myopathy (CNM)." (PMID 31680794, 2019). "We also provide in vivo evidence in the congenital myotubular myopathy mouse model (knock-out for the myotubularin coding gene Mtm1) that a down-regulated myostatin pathway can be reactivated by correcting the underlying gene defect." (PMID 29192144, 2017). "In particular, myotubularin 1 (MTM1) mutations lead to X-linked myotubular myopathy, and Jumpy (MTMR14) mutations cause congenital disease centronuclear myopathy." (PMID 23630012, 2013). "X-linked centronuclear myopathy (XLCNM, also called myotubular myopathy; OMIM 310400) is a recessive congenital muscle disorder affecting mainly males and due to mutations in the MTM1 gene coding for the phosphoinositides (PPIn) phosphatase myotubularin." (PMID 23071445, 2012). "In zebrafish, knockdown of MTMR14 was shown to cause a similar increase in autophagy (as measured by LC3-II levels) and double knockdown studies with MTM1 resulted in a phenotype reminiscent of human centronuclear myopathy." (PMID 21256213, 2011). "Here we show that inactivation of the kinase activity of PI3KC2β is sufficient to efficiently rescue the motor behavior, muscle atrophy, muscle weakness, the histopathology, and sarcomere and triad organization defects of the Mtm1-KO mouse model of myotubular myopathy." (PMID 36943412, 2023). "The most severe form linked to MTM1 mutations is X-linked CNM, also called myotubular myopathy." (PMID 36943412, 2023). "In conclusion, while the PI3KC2β kinase-dead mutation rescues the Mtm1-KO mouse model for myotubular myopathy linked to MTM1 loss, it does not improve the Bin1mck–/– mouse model for autosomal recessive CNM." (PMID 36943412, 2023). "Finally, MTM1 was found to interact with the striated muscle enriched protein kinase SPEG; mutations in SPEG have been linked to centronuclear myopathies with disruptions of triadic structures and impairment of ECC." (PMID 35454077, 2022). "It should be noted, however, that such effects of tamoxifen were administered to mice with impaired muscle function, that is, to mdx mice (mouse model of Duchenne muscular dystrophy), to FKRPP448L mutant mice with dystroglycanopathy, and to Mtm1 knockout mice (murine model of myotubular myopathy)." (PMID 35929607, 2022). "Indeed, Tasfaout and collaborators succeeded to revert the phenotype of MTM1‐myotubular myopathy mouse model by knock‐down Dnm2 using anti‐sense oligonucleotide." (PMID 29246969, 2018). "These include mutations in myotubularin 1 (MTM1) and myotubularin-related protein 14 (MTMR14) that are associated, respectively, with X-linked myotubular myopathy and congenital disease centronuclear myopathy." (PMID 27484057, 2016). "Centronuclear myopathy (CNM), a severe congenital myopathy characterized by T-tubule defects and muscle weakness, is associated with mutations in three membrane trafficking-related genes: BIN1 (Bridging Integrator-1; also known as Amphiphysin 2, Amph2), DNM2 (Dynamin 2), and MTM1 (Myotubularin 1)." (PMID 41499502, 2026). "This increased expression of SAR1A is specific to KLHL40-deficient skeletal muscle as analysis of skeletal muscle from centronuclear myopathy patients (RYR1 or MTM1 disease-causing mutations) showed no changes in the SAR1A protein levels compared to the control." (PMID 37432316, 2023).
myotubular myopathy (continued). "X-linked CNM (XLCNM, also called myotubular myopathy) is caused by mutations in the phosphoinositide phosphatase myotubularin (MTM1; MIM#310400) and autosomal dominant and recessive CNM due to mutations in the DNM2 partner amphiphysin 2 (BIN1; MIM#255200)." (PMID 36369230, 2022). "To identify BIN1 mutations affecting its function in skeletal muscle, we sequenced the muscle-specific exon 11 and the adjacent splice-relevant intronic regions in a cohort of 84 patients with various forms of centronuclear myopathy and without mutations in MTM1, DNM2, or in the other BIN1 exons." (PMID 23754947, 2013). "Similarly, mtm1 zebrafish morphants and mtm-depleted drosophila muscles display structural defects of the triads, and such defects have been also observed in muscles from patients with myotubular myopathy." (PMID 21797990, 2011). "Knockdown of centronuclear myopathy genes Bin1b (OMIM: 255200) and MTM1 (OMIM: 310400), which disrupt T‐tubule formation, also disrupted myotome acidification." (PMID 39840753, 2025). "Necklace fibres with nuclear internalisation have been reported as a histological hallmark of X-linked myotubular myopathy related to mutations in the phosphoinositide phosphatase myotubularin 1 (MTM1) gene and also a late-onset dynamin-2 (DNM2) gene-related centronuclear myopathy." (PMID 32444983, 2020). "However, we speculate that the mechanism responsible for these observed multinucleated fibers is not the same as in centronuclear myopathies caused by mutations in BIN1, MTM1, or DNM2, as classically those result in the persistence of myofibers with a single, well-centralized nucleus." (PMID 39264856, 2024).